FLCN (folliculin)
Diseases named in the same sentence as FLCN in open-access papers (continued):
Sharing a sentence is not in itself a finding about the gene and the disease.
renal tumors (continued). "FLCN deficiency promoted STAT2 recruitment to chromatin and decelerated cell proliferation, underscoring the FLCN and FNIP1/FNIP2 complex’s distinctive role in the development of human renal tumors and identifying potential prognostic biomarkers." (PMID 40143966, 2025). "After excluding benign renal neoplasia (such as oncocytoma and angiomyolipoma), alterations of BAP1, FLCN, and MITF were identified in 5 of 81 patients (6.2%) with melanoma and/or mesothelioma and renal neoplasia." (PMID 34767027, 2021). "Family history of pulmonary cysts/spontaneous PTX and renal tumors as well as characteristic radiologic features was strongly suggestive of BHD syndrome and prompted us to perform FLCN genetic testing." (PMID 27871249, 2016). "FLCN is considered a tumor suppressor, following the Knudson “second hit” model, since somatic mutation or loss of heterozygosity of the non-affected allele has been observed in BHD-associated renal tumors and in animal models." (PMID 33981707, 2021). "However, given the association of hereditary predisposition syndromes in patients with melanoma and/or mesothelioma with renal neoplasia, universal screening may be warranted in this patient population with a panel that includes BAP1, MITF, and FLCN." (PMID 34767027, 2021). "Furthermore, immunostaining of FLCN and HIF2α in these 75 primary renal tumors revealed a negative correlation in expression (r = −0.4534, P < 0.01)." (PMID 32850947, 2020). "Importantly, we show that glycogen accumulates in kidneys from mice lacking FLCN and in renal tumors from a BHD patient." (PMID 26439621, 2015). "Although BHDS is exceedingly rare, it is important to determine whether molecular analysis of BHDS-derived renal tumors could give insight into the development of sporadic chromophobe RCC and renal oncocytoma as well as the cellular role of FLCN-related signal transduction." (PMID 21162720, 2010). "Based on our findings, it is likely that a FLCN-PGC-1α-TFAM signaling axis exists and that lack of FLCN expression may be an important feature in sporadic tumors of other organs as it is in BHDS-derived renal tumors." (PMID 21162720, 2010). "The number of genes within a panel may be as few as six (e.g. BAP1, FH, FLCN, MET, SDHB, and VHL genes) though commercial genetic testing companies may offer larger gene panels (18–30 genes but including some for non-RCC kidney tumours;)." (PMID 38802529, 2024).
renal carcinoma (43 papers, 2008 to 2025). A carcinoma arising from the epithelium of the renal parenchyma or the renal pelvis. "Previous studies indicate distinctive cytogenetic features in FLCN mutation related RCC compared to sporadic RCC.A study from Japan found that 34.8% of individuals carrying FLCN mutations aged over 40 had been diagnosed with renal cancers." (PMID 39300538, 2024). "Future studies with larger cohorts recruited from multidisciplinary approach are needed to explore the relationship between renal cancer and specific FLCN mutations." (PMID 37170274, 2023). "The enhanced phosphorylation of EGFR, MET, and EPHA2/B1 upon FLCN loss is interesting in light of previous studies that linked these kinases to renal cancer." (PMID 35863698, 2022). "In Birt–Hogg–Dubé (BHD) syndrome, germline loss-of-function mutations in the Folliculin (FLCN) gene lead to an increased risk of renal cancer." (PMID 35863698, 2022). "In Birt–Hogg–Dubé (BHD) syndrome, germline mutations in the Folliculin (FLCN) gene predisposes carriers to an increased risk of renal cancer." (PMID 35863698, 2022). "The FLCN gene is a tumor suppressor, but the mechanism by which FLCN deficiency causes renal cancer is not completely understood." (PMID 32850947, 2020). "Birt-Hogg-Dubé (BHD) Syndrome is a rare genodermatosis caused by a mutation on folliculin gene, with a strong link to renal cancer." (PMID 30326848, 2018). "Because inactivating mutations in the BHD gene encoding Folliculin result in renal cancer, we sought to determine if loss of Fnip1 alters kidney development and/or function in Fnip1-null mice, which were previously generated using ENU chemical mutagenesis." (PMID 29897930, 2018). "FNIP degradation facilitated the replacement of FLCN by mTOR on the lysosomal surface, which, in turn, activated mTORC1 signaling associated with renal cancer development and progression." (PMID 28039480, 2017). "Taken together, these data indicate a critical tumor suppressive role of the FLCN complex in BHD-associated renal cancer proliferation and tumorigenesis, and β-TRCP counteracts the observed tumor suppressive function through FNIP degradation." (PMID 28039480, 2017). "Degradation of FNIP2 leads to lysosomal dissociation of FLCN and subsequent lysosomal association of mTOR, which in turn promotes the proliferation of renal cancer cells." (PMID 28039480, 2017). "We compared the analysed the radiological findings to those in 4 proven FLCN mutation carriers with renal cancer." (PMID 26603437, 2016). "Suppression of autophagy further enhances paclitaxel-induced apoptosis in FLCN-deficient renal cancer cells." (PMID 24305604, 2013). "In summary, our data demonstrated that in FLCN-deficient renal cancer cells, paclitaxel treatment induced apoptosis is associated with increased autophagy that plays a protective role against the treatment." (PMID 24305604, 2013). "The European BHD Consortium proposed FLCN mutation testing in patients with early-onset renal cancer (<50 years), in particular with multifocal or bilateral disease (or both) with chromophobe or oncocytic histology and in familial renal cancer cases." (PMID 22146830, 2011). "In all, 14 out of 115 (12%) FLCN mutation carriers from 12 families were diagnosed with renal cancer." (PMID 22146830, 2011). "Among 14 FLCN mutation carriers who developed renal cancer 7 were <50 years at onset and/or had multifocal/bilateral tumours." (PMID 22146830, 2011). "The clinical presentation, histological pattern and biological behaviour of renal cancer in FLCN mutation carriers are important for several reasons." (PMID 22146830, 2011). "The renal cancer risk we found of around 16% at age 70 years is important for counselling of FLCN mutation carriers and their families ascertained in cancer family clinics." (PMID 22146830, 2011). "The estimated renal cancer penetrance based on assessment of FLCN mutation carriers only was 20% at age 70 (red dashed line)." (PMID 22146830, 2011).
renal carcinoma (continued). "We confirmed a high yield of FLCN mutations in clinically defined BHD families, we found a substantially increased lifetime risk of renal cancer of 16% for FLCN mutation carriers." (PMID 22146830, 2011). "Birt-Hogg-Dube' (BHD) syndrome is characterized by the development of fibrofolliculomas, lung cysts and renal carcinoma and caused by germline mutations in the folliculin (FLCN) gene." (PMID 21209915, 2010). "Using a FLCN-deficient kidney model, it was found that FLCN loss upregulates PGC1α expression, which results in elevated mitochondrial function and oxidative metabolism in renal cancer cells." (PMID 41206543, 2025). "Using a FLCN-deficient kidney model, it was found that FLCN loss leads to increased PGC1α expression, which results in elevated mitochondrial function and oxidative metabolism in renal cancer cells." (PMID 33981707, 2021). "Interestingly, the tumorigenic potential of FLCN-deficient renal cancer cells is inhibited by sirolimus, a mTOR inhibitor." (PMID 32751108, 2020). "PGC1α levels were found to be elevated in FLCN-deficient renal cancers." (PMID 32751108, 2020). "To determine whether paclitaxel induces autophagy as well in FLCN-deficient renal cancer cells, we measured the expression of microtubule-associated protein 1 light chain 3 (LC3) in paclitaxel-treated cells by Western blot." (PMID 24305604, 2013). "Our findings suggest that paclitaxel treatment combined with inhibition of autophagy might be a potentially more effective chemotherapeutic approach for FLCN-deficient renal cancer and BHD-related kidney tumors." (PMID 24305604, 2013). "Our results suggest that paclitaxel combined with an autophagy inhibitor might be a potentially more effective chemotherapeutic approach for FLCN-deficient renal cancer." (PMID 24305604, 2013). "Accordingly, inactivating alterations in FLCN also drive a rare subset of PEComas, in addition to renal carcinomas that bear resemblance to tRCC21–23." (PMID 41044182, 2025). "Dysfunction of the Rags can also promote tumorigenesis, as seen in the case of RagC mutations in follicular lymphoma and mutations of FLCN, a RagC/D activator, in BHD syndrome, which is associated with renal cancer." (PMID 38987251, 2024). "FLCN sequencing should be taken into account in patients and their families since the incidence of renal cancer in BHD patients is very high, and detection at early stages can prevent its metastasis." (PMID 35237525, 2022). "In conclusion, we demonstrate the specific mechanism by which FLCN regulates HIF2α-induced renal cancer cell proliferation, migration, and invasion." (PMID 32850947, 2020). "Based on the analysis of 75 groups of renal cancer tissues and para-cancerous tissues, we found that the FLCN expression level was low in tumor tissues, while the HIF2α expression level was in a reversed pattern." (PMID 32850947, 2020). "Single allele loss of FLCN is ascribed to an occurrence of the syndrome, and a mutation in the second allele or loss of heterozygosity leads to BHD-associated renal cancer development." (PMID 28039480, 2017). "In contrast, pAKT was expressed exclusively in the renal cysts in FLCN KO mouse kidneys, while pSTAT3 and pERK were highly expressed throughout the cysts and in the renal carcinomas." (PMID 28656962, 2017). "Recent studies indicated that FNIP1/FNIP2 double knockout mice display enlarged polycystic kidneys and renal carcinoma, which phenocopies FLCN knockout mice, suggesting that these two proteins function together to suppress renal cancer." (PMID 28039480, 2017). "In this study, we identified that nutrient-sensitive proteasome-dependent FNIP degradation promoted renal cancer development by suppressing the formation of the FLCN complex." (PMID 28039480, 2017). "Mutations in FLCN are associated with Birt-Hogg-Dubé (BHD) syndrome, a rare disorder with increased risk of renal cancer." (PMID 28039480, 2017).
renal carcinoma (continued). "Germline mutations in the Folliculin (FLCN) tumour suppressor gene result in fibrofolliculomas, lung cysts and renal cancers, but the precise mechanisms of tumour suppression by FLCN remain elusive." (PMID 28656962, 2017). "In summary, with the current study, we have provided first evidence for a direct connection between the VHL and FLCN tumor-suppressing pathways converging on regulation of autophagy in renal cancer." (PMID 23922894, 2013). "We found that GPNMB expression, which is regulated by MiTF, was greatly elevated in renal cancer cells harboring either TFE3 translocations or FLCN inactivation." (PMID 21209915, 2010). "GPNMB expression was investigated in renal cancer cells, mouse embryo fibroblast cells, and mouse and human renal carcinomas under conditions of FLCN inactivation." (PMID 21209915, 2010). "TFE3 knockdown reduced GPNMB expression in renal cancer cells harboring either TFE3 translocations or FLCN inactivation." (PMID 21209915, 2010). "Heterozygous FNIP1/homozygous FNIP2 double knockout mice developed renal cancer at 24 months, akin to heterozygous FLCN knockout mouse models, thereby reinforcing the significance of FNIP1 and Fnip2 in tumor suppression and suggesting potential molecular targets for novel renal cancer therapies." (PMID 40143966, 2025). "However, an in-depth understanding of the role of folliculin in the molecular pathogenesis of renal cancer requires further study." (PMID 35664771, 2022). "It has been suggested that certain FLCN variants lead to a forme fruste of BHDS with pneumothoraces but no renal cancers." (PMID 34267338, 2021). "Our findings point out that FLCN/HIF2α expression may be a novel therapeutic target for preventing renal cancer proliferation and invasion." (PMID 32850947, 2020). "Germline mutations in the folliculin (FLCN) tumor suppressor gene are linked to Birt-Hogg-Dubé (BHD) syndrome, a dominantly inherited genetic disease characterized by predisposition to fibrofolliculomas, lung cysts, and renal cancer." (PMID 33137092, 2020). "We also determined the correlation of FLCN and HIF2α in human renal cancer samples." (PMID 32850947, 2020). "FLCN interacts with HIF2α and promotes HIF2α degradation in human renal cancer cells." (PMID 32850947, 2020). "Although the current study has contributed to the mechanistic understanding of the role of FLCN in regulating renal cancer cell physiological activities, the issue as to how FLCN precisely adjusts HIF2 degradation in ccRCC cells is unlikely to be settled in this paper." (PMID 32850947, 2020). "In addition, we found that FLCN‐deficient HEK293 cells and UOK‐257 cells, which are derived from a BHD patient's renal carcinoma, display a striking increase in cell‐–cell adhesion relative to control FLCN‐expressing cells." (PMID 25121506, 2014). "Our results indicated that autophagy induced by paclitaxel in FLCN-null renal cancer cells plays a protective role, and the inhibition of autophagy could increase apoptosis induced by paclitaxel treatment in these cancer cells." (PMID 24305604, 2013). "In addition, FLCN mRNA and protein expression were repressed in Caki1 renal cancer cells in which we knocked down endogenous VHL expression by using shRNA." (PMID 23922894, 2013). "Recently folliculin (FLCN), a tumour suppressor mutated in Birt–Hogg–Dubé syndrome leading to renal cancers, which had no homologies according to PSI-BLAST, was identified as a structural and functional homologue of DENN." (PMID 23329412, 2013). "BHD syndrome, caused by FLCN mutations, is an autosomal dominant genetic disease characterized by susceptibility to renal cancer, renal and pulmonary cysts, and noncancerous tumors of the hair follicles." (PMID 24305604, 2013). "In our study, we observed that autophagy was obviously activated by paclitaxel via the MAPK pathway and beclin 1 protein in FLCN-deficient renal cancer cells, but not in FLCN-expressing cells." (PMID 24305604, 2013).
renal carcinoma (continued). "Two additional patients from FLCN positive families but with unknown mutation carrier status (BHD 1 and BHD 42) were diagnosed with renal cancer." (PMID 22146830, 2011). "Thus it is likely that elevated TFE3 transcriptional activity as a consequence of FLCN inactivation contributes to the development of renal carcinoma." (PMID 21209915, 2010). "Interestingly, it has been suggested that certain FLCN variants lead to a form of BHDS with PNXs but no renal carcinomas, although the risk of developing fatal renal cancers with crucial consequences is high." (PMID 35237525, 2022). "In order to investigate whether the in vitro experimental findings were consistent with the pathogenesis and the progression of renal cancer in humans, we examined the FLCN and the HIF2α expression patterns in renal cancers (75 paired cases) by a tissue microarray." (PMID 32850947, 2020). "Moreover, FLCN knockdown induced GPNMB expression in FLCN-restored renal cancer cells." (PMID 21209915, 2010). "However, none of these renal cancer cell lines harbored a mutation in FLCN." (PMID 35863698, 2022). "Collectively, these studies suggest that disruption of Folliculin is sufficient to result in the development of PKD, and can in some cases progress to renal cancer due in part to increased activation of the mTOR pathway and increased mitochondrial biogenesis." (PMID 29897930, 2018). "VHL, MET, folliculin (FLCN), tuberous sclerosis 1 (TSC1), TSC2, fumarate hydratase (FH) and succinate dehydrogenase (SDH) are known as renal cancer genes, and all are involved in pathways that respond to metabolic stress or nutrient stimulation." (PMID 24348776, 2014). "The results show the existence of functional crosstalk between two major tumor suppressors in renal cancer, VHL and FLCN, converging on regulation of autophagy." (PMID 23922894, 2013). "Notably, the lifetime renal cancer risk for FLCN mutation carriers has not yet been established." (PMID 22146830, 2011). "Although our patient tested negative for 19 genes known to cause renal cancer syndromes, including FH, VHL, FLCN, and MET, the possibility that the patient has a coexisting autosomal dominant renal cancer syndrome is unlikely but cannot be excluded." (PMID 38802873, 2024). "We examined the FLCN and HIF2α expression patterns in renal cancers (75 paired cases) by a tissue microarray; FLCN and HIF2α showed a negative correlation." (PMID 32850947, 2020). "Methylation inactivation of tumor suppressor genes, such as FLCN and DDIT3, is important for the development of many cancer, such as renal cancer and gastric cancer, but inactivation of these genes may be responsible for the advancement of BRCA." (PMID 31311202, 2019). "Although disruption of Folliculin is known to predispose to renal cancer in humans, and PKD and renal cancer in mice, a specific role for Fnip1 has not been previously demonstrated." (PMID 29897930, 2018). "To further determine the cellular response of FLCN-deficient cell lines treated with paclitaxel, here we examined apoptosis and autophagy induced by paclitaxel in human renal cancer cell lines with or without FLCN expression." (PMID 24305604, 2013). "In this report, we investigate the cellular and molecular mechanism of paclitaxel-induced autophagy and apoptosis in renal cancer cells with and without FLCN expression." (PMID 24305604, 2013). "Interestingly, FLCN, like tumor suppressor VHL, seems to be associated with the activity of LC3-mediated autophagic program, which suggests that the existence of functional crosstalk between two major tumor suppressors in renal cancer, VHL and FLCN, converging on regulation of autophagy." (PMID 24305604, 2013). "After paclitaxel treatment, a dose-dependent decrease in cell viability and increase in apoptosis were observed in FLCN-deficient UOK257 and ACHN-5968 cells compared to their FLCN-expressing counterparts, suggesting that renal cancer cells without FLCN were more sensitive to paclitaxel." (PMID 24305604, 2013).
renal carcinoma (continued). "In order to confirm whether FLCN bound to HIF2α directly, we further identified the protein interaction in ACHN cells by co-immunoprecipitation and the endogenous protein interaction between renal cancer cells and normal renal tubular epithelial cells by immunoprecipitation." (PMID 32850947, 2020).